CD4 (CD4 molecule)
Diseases named in the same sentence as CD4 in open-access papers (continued):
Sharing a sentence is not in itself a finding about the gene and the disease.
bladder cancer (continued). "Treated with CTLA-4 blockade, ICOS expressed higher on CD4+ T cells from peripheral blood and tumor tissues of bladder cancer patients and this CD4+ICOShi T cell population produced higher IFN-γ, indicating that ICOS interacts with CTLA-4 and plays an important role in tumor immunity." (PMID 21917182, 2011). "Therefore, driving EMT in bladder cancer might be another mechanism by which PD1hi CD200hi CD4+ exhausted T cells promote immune escape in bladder cancer, in addition to inducing angiogenesis." (PMID 37313656, 2023). "Consequently, we hypothesized that PD1hi CD200hi CD4+ exhausted T cells may promote EMT in bladder cancer cells, thus contributing to immunotherapy resistance." (PMID 37313656, 2023). "Therefore, it is necessary to explore the role of CD4+ exhausted T cells in bladder cancer." (PMID 37313656, 2023). "An increasing number of studies have shown that CD4+ T cells are susceptible to exhaustion and may contribute to the reactivation of the antitumour immune response after ICI treatment in multiple cancer types, including bladder cancer." (PMID 37313656, 2023). "Finally, our findings suggest that immunotherapy combined with anti‐CD200 drugs might be a promising therapeutic option for bladder cancer patients with high proportions of PD1hi CD200hi CD4+ exhausted T cells." (PMID 37313656, 2023). "However, whether and how CD4 CTLs can eliminate bladder cancer cells in vivo remain to be determined." (PMID 35572552, 2022). "Similar to the outcome obtained in the mouse bladder cancer model, the OMV-Ps resulted in elevated levels of CD8+ effector T cells, CD4+ memory T cells, and CD8+ memory T cells in PBMCs and dLNs in the mouse LLC model." (PMID 38166929, 2024). "In a mouse bladder cancer tumor model, the antitumor effects of BCG immunotherapy were lost when CD4+ or CD8+ T cells were depleted, indicating their crucial role in the induced antitumor activity of BCG9." (PMID 38213738, 2024). "BCG also stimulates a TH1 response by activating CD4+ T cells, which are considered essential for BCG‐mediated effects on bladder cancer." (PMID 38553868, 2024). "To verify the function of PD1hi CD200hi CD4+ exhausted T cells in vivo, we subcutaneously implanted MB49 bladder cancer cells into immunocompetent mice and treated mice every 2 days with anti‐PD1 antibody when tumours were 50 mm3 in size." (PMID 37313656, 2023). "Finally, multiplex immunofluorescence was performed to determine the infiltration of PD1hi CD200hi CD4 exhausted T cells in bladder cancer tissue, which showed that PD1hi CD200hi CD4 exhausted T cells were commonly present in the tumour‐infiltrating CD4+ T cells in the bladder cancer tissues." (PMID 37313656, 2023). "FUT7 promoted the proliferation, migration, invasion, and EMT of bladder cancer cells, and positively correlated with immune cell infiltration levels (CD8+ T cells, CD4+T cells, macrophage, neutrophil, and DCs)." (PMID 35784355, 2022). "Using the GEPIA2021 deconvolution tool for the TCGA bladder cancer cohort, we found that HNRNPU was significantly decreased in B cells, CD4+ T cells, and CD8+ T cells." (PMID 35130920, 2022). "In the mouse bladder cancer model, NCTD treatment increased CD4+ T and CD8+ T frequency in tumor sites and in peripheral blood." (PMID 35409302, 2022). "A few studies have suggested that bladder cancer cells could initiate an immune response by presenting antigen to CD4 T cells; however, the ability to effectively present antigen and activate CD4 T cells is generally limited to professional antigen presenting cells." (PMID 35804844, 2022). "After BCG intravesical treatment on an experimental study of bladder cancer, the authors detected a higher number of CD4 T-cells infiltrating the tumor (TIL) and correlated it with increased IFN-γ by these specific CD4 T cells." (PMID 34062708, 2021).
bladder cancer (continued). "In addition, a recent study found that a cytolytic population of CD4+ T cells contributes significantly to anti-tumor immune activity in bladder cancer patients, and their infiltration into metastatic bladder tumors could predict clinical response to anti-PD-L1 therapy." (PMID 33671373, 2021). "In bladder cancer, a larger ratio of CD8+T cell/CD4+T cell indicates a more rapid tumor growth and a better response to immunotherapy." (PMID 34422050, 2021). "In this study, four kinds of immune cells were related to the survival of patients with bladder cancer, including T cell CD8, T cell CD4 memory resting, T cell CD4 activated, and NK cell resting." (PMID 32010623, 2019). "Consistent with our data, a small proportion of Tregs co-expressed CD103 and the percentage of CD4+CD103+ TILs was much lower than CD8+CD103+ TILs in patients with ovarian and bladder cancers." (PMID 28099920, 2017). "We found that the number of CD4+, CD8+, CD25+, FoxP3+ and CD20+ TILs and the frequency of blood Tregs changed with the progression of the urinary bladder cancer." (PMID 26927070, 2016). "However, the CD4+:CD8+ TIL ratio was significantly lower in the group with the recurrence, or more specifically, this group had a greater number of CD8+ TILs, thus indicating that CD8+ TILs could be associated with bladder cancer recurrence." (PMID 23275325, 2012). "The median CD4+ cell count in our series was 280 cells/mm3 and the average duration of HIV infection was 8 years prior to diagnosis of bladder cancer." (PMID 19719844, 2009). "Immunohistochemistry staining in bladder cancer tissues further validated that strong staining of IFNG was observed near the tumour borders rather than around PD1hi CD200hi CD4+ exhausted T cells." (PMID 37313656, 2023). "In contrast to kidney tumors, MB49 bladder cancers were infiltrated by a significant number of tumor-resident CD8 T cells (>20% of total CD3+ T cells on average), and regulatory T cells were dominating the CD4 T-cell population (>50% of CD4 T cells)." (PMID 38259453, 2023). "Overall, the PD1hi CD200hi CD4+ T cells might be recruited and contribute to the EMT of bladder cancer cells through m6A‐mediated GAS6." (PMID 37313656, 2023). "The results above indicated that the GAS6–AXL axis might interact with the PD1hi CD200hi CD4 exhausted T cells, trigger EMT and promote bladder cancer progression." (PMID 37313656, 2023). "Future studies will need to show whether similar anti-tumour responses can be created using CD4+ CTLs within their natural MHC-II context, as seems to be the case for bladder cancer." (PMID 37122720, 2023). "Furthermore, immune cell infiltrate analysis indicated B cells, CD4+T cells, and CD8+T cells were significantly different across high HSPB8 expression group and low HSPB8 expression group in bladder cancer." (PMID 37404760, 2023). "The miR-106a-5p miRNA, has a strong connection to the regulation of CD4 + T-cells and functions as a tumor suppressor, and miR-125b-5p is interrelated with suppressing PI3K/AKT pathway in bladder cancer and the miR-125a-5p is connected with the macrophages inflammatory response." (PMID 37993790, 2023). "Moreover, PD1hi CD200hi CD4+ exhausted T cells can promote EMT and angiogenesis in bladder cancer cells in vitro." (PMID 37313656, 2023). "In the MB49 bladder cancer model, mice that rejected their tumors following CpG treatment developed tumor-specific immunity which was abrogated by CD4+ T cell depletion but not CD8+ T cell depletion." (PMID 36159781, 2022). "First, co-culture of CD4+ T cells promoted the proliferation and invasion of bladder cancer cells and considerably increased the expression of not only MET oncogene and c-MET but also ERβ in bladder cancer cells." (PMID 33796076, 2021).
bladder cancer (continued). "Bladder cancer-infiltrating CD4+FOXP3+ T cells did not produce IL-2 or IFN-γ even upon stimulation, and readily suppressed autologous CD4+ effector T cells, confirming that tumor-infiltrating CD4+FOXP3+ T cells act functionally as T regs." (PMID 31811337, 2020). "Increased frequency of CD4+ regulatory T cells in draining-lymph nodes of bladder cancer patients suggests a negative role for these cells in antitumor immune responses." (PMID 33305045, 2020). "Finally, the results showed that CD4 and CD8 T cells increased in the high-TMB group of bladder cancer." (PMID 31534952, 2019). "Our study found that CD4 and CD8 T cells, as well as NK cells, may be major players in antitumor immunity in bladder cancers with high-TMB." (PMID 31534952, 2019). "However, to our knowledge there have been no studies that have examined the relationship between tumour CD4+ and CD8+ T-lymphocytic infiltration and cancer-specific survival in patients with bladder cancer." (PMID 17024120, 2006). "Furthermore, rBCG-S1PT improved activation markers on CD4+ T cells and exerted greater cytotoxicity against MB49 bladder cancer cells, suggesting it could potentially be an enhanced immunotherapy for bladder cancer." (PMID 40747468, 2025). "The high proportion of naive CD4+ T cells suggests that the immune system is not effectively activated, enabling bladder cancer cells to evade immune surveillance and promote cancer development, consistent with HLA-DR+ CD8 bright T cells acting as a protective factor." (PMID 40427030, 2025). "PBMCs from individuals with Sh-associated bladder cancer had lower CD3+ T cells compared to Sh-unassociated bladder cancer, while CD4+ T cells, Tregs, and Bregs were higher in Sh-unassociated bladder cancer compared to healthy controls who did not have Sh infection or bladder cancer." (PMID 39250522, 2024). "Thus, we proposed that PD1hi CD200hi CD4 exhausted T cells and malignant cells may communicate via AXL–GAS6 signalling in bladder cancer." (PMID 37313656, 2023). "However, studies have only observed a significant increase in the level of CD4+ cells (specifically Th17 cells) in the blood of bladder cancer patients; thus, the role of tumor-infiltrated CD4+ cells has not been elucidated." (PMID 33465047, 2021). "Therefore, we proposed that PD1hi CD200low CD4+ exhausted T cells in the TME might induce the expansion and activation of intratumoural CD8+ T cells, thus leading to better immunological responses in bladder cancers patients." (PMID 37313656, 2023). "S100A5 expression was the highest in epithelial cells, whereas no expression was observed in immune cells (such as CD4+ T, CD8+ T and NK cells) using another scRNA‐seq database containing two bladder cancer specimens (GSE130001)." (PMID 37414584, 2023). "A detailed analysis also revealed that the levels of effector T cells, CD4+ and CD8+, were significantly lower in the late phase of tumor development (pT3–pT4) and in bladder cancers that developed non-classic differentiation (NDN > 0)." (PMID 26927070, 2016). "Taken together, our data show that CD4+ and CD8+ T cells but not NK and NKT cells are the prominent mediators for combination therapy of bladder cancer." (PMID 27498556, 2016).
liver disease (136 papers, 2010 to 2026). "Analysis of RNA-seq data confirmed the presence of salt-induced and pathogenic Th17 signatures in liver and peripheral CD4+ samples of patients with liver disease." (PMID 40705454, 2025). "Liver disease progression was associated with lower nadir CD4+ T-cell count and higher levels of HMGB1 at baseline." (PMID 38518655, 2024). "Transmission via IDU and lower CD4 count at ten years after starting ART were strongly associated with mortality from liver-disease." (PMID 27525413, 2016). "We also found that liver disease in this group was strongly associated with CD4+ T cell count≤350 cells/μL using APRI and FIB4, as was demonstrated in a US-based study." (PMID 26979535, 2016). "One possible explanation for the higher prevalence of moderate-to-significant liver disease in our cohort is that our participants had lower median CD4+ T cell counts, which we found to be an independent risk factor for elevated APRI and FIB-4." (PMID 26979535, 2016). "In the subset of HIV monoinfected subjects, CD4 count below 350 cells/μL was associated with moderate-to-significant liver disease by both APRI (OR 1.82, 95% CI 1.02–3.25) and FIB4 (OR 1.98, 95% CI 1.11–3.52) scores." (PMID 26979535, 2016). "Collectively, in patients with chronic HBV infection, the frequencies of blood CXCR5+CD4+ T cell and B cells were associated with liver disease activity." (PMID 27612199, 2016). "CVID patients with lower naïve CD45RA+CD4+ T-cells or severely reduced B-cells might be at higher risk for portal hypertension." (PMID 38187397, 2023). "CD4+ T cells play an essential role in orchestrating adequate immunity, but their overactivity has been associated with the development of immune-mediated inflammatory diseases, including liver inflammatory diseases." (PMID 34463867, 2021). "In the present study, the HBcAg mutations that were associated with advanced liver disease were derived from all three epitope types (B-cell, CD4+ T-cell, and CD8+ T-cell), suggesting a complex interplay between the virus and the host throughout the course of chronic HBV infection." (PMID 30406036, 2018). "It is unclear whether the CD4-cell count or the CD4 nadir is associated with the progression of liver disease." (PMID 23226258, 2012). "TGF-β1 stimulates the differentiation of Th17 cells, boosts the activities of CD4+ regulatory T cells, and contributes to liver disease progression." (PMID 39878655, 2025). "Upon the release of ROS during liver disease progression, KCs and MO-Mφs are activated and secrete divers chemokines to recruit monocytes, other leukocytes, CD4+ and CD8+ T cells." (PMID 40684220, 2025). "This reduction was due to decreased frequencies of CD8+ T cells, whereas frequencies of CD4+ T cells were relatively stable with worsening liver disease." (PMID 41028194, 2025). "This study provides a comprehensive analysis of circulating CD8+ and CD4+ T cells in patients across different stages of liver disease and unravels the soluble immune milieu present in the peripheral blood of patients with decompensated liver cirrhosis." (PMID 41028194, 2025). "Patients with other liver diseases display portal hypertension and cirrhosis, with both splenomegaly and hypersplenism associated with a high CD4+/CD8+ ratio, but a low Treg+/CD4+ ratio." (PMID 39358604, 2024). "Triple infection with HIV/HBV/HDV requires integrated care models to address both immune suppressions as indicated by diminished CD4 cell count and liver disease progression, as these patients face worse outcomes." (PMID 39599836, 2024). "Factors which predicted in-hospital mortality included ART interruption, CD4 + cell counts ≤ 200 cells/μL, undocumented CD4 + cell counts, function impairment, co-infections, liver disease and long distance from the hospital." (PMID 38388345, 2024). "Treg cells, accounting for 5–10% of CD4+ T cells, are crucial for maintaining immune homeostasis and tolerance in liver disease and transplantation." (PMID 36902432, 2023).
liver disease (continued). "Those with CD4 < 200 were more likely than those with higher CD4 to have many comorbidities including liver disease, kidney disease, malignancy, congestive heart failure, and dementia (p-trend <0.0001 for all)." (PMID 38356736, 2023). "Other factors associated with HCV coinfection among Asian adult PLHIV include older age, lower education, lower CD4 cell count, and having a household member with liver disease." (PMID 37379314, 2023). "As cirrhosis mediates the causal pathway to HCC, patients with CHB-induced HCC often have a certain degree of sclerosis and portal hypertension, and their CD4+ T cells levels are often lower than normal." (PMID 35321670, 2022). "Comorbidities such as cirrhosis (OR 8.95 (4.0–15.99)), other liver diseases (adjusted OR 7.78 (3.43–17.64)), or having low CD4 counts (OR 0.96 (0.94–0.99) for a CD4 increase of 10 counts) increased the odds of having HEV." (PMID 35648773, 2022). "Hepatitis B virus-related HCC is often accompanied by cirrhosis and portal hypertension; therefore, CD4+ tend to be relatively low in number." (PMID 35321670, 2022). "Given that the CD4/CD8 ration is decreased in other liver diseases if the disease is worsening, we analyzed this in our splenectomy emAIH model." (PMID 36496477, 2022). "Considering that T cells, in particular CD4+ T cells, play a key role in both NASH and AIH, here we will dissect the contribution of the different subsets of CD4+ T cells in the pathogenesis of these immune-mediated inflammatory liver diseases." (PMID 34463867, 2021). "Among all participants, 112 (45%) were on WHO clinical stage II, 111 (44.6%) had CD4 count of less than 200 cells/mm3, and 12 (4.8%) had a history of liver disease." (PMID 33552160, 2021). "As an emerging CD4+Th cytokine, IL-22 plays an overwhelming hepatoprotective and regenerative roles in various liver diseases with the activation of STAT3 pathway." (PMID 32760208, 2020). "In the present study, we investigated the phenotype and plasticity of hepatic ILC2 in response to liver inflammation-induced cytokines and effector CD4+ T cells in order to identify mechanisms of ILC2 regulation in liver disease." (PMID 31974518, 2020). "Biliary atresia (BA) is a destructive pediatric liver disease and CD4+T cell activation is demonstrated to play an important role in BA." (PMID 31355166, 2019). "For cholangitis, CXCR3 is likely to not only directly regulate CD8+ T cells and their IFN-γ production to ameliorate liver disease but also regulate CD4+ T cells to affect the function of CD8+ T cells indirectly." (PMID 29868034, 2018). "CD4 discordance has been shown also to correspond with advanced liver disease when assessed by transient elastography." (PMID 27471521, 2016). "We compared the frequency and surface phenotype of liver‐infiltrating CD4+CD25highCD127low Treg (LITreg) in different inflammatory liver diseases with normal liver tissue and with liver‐infiltrating CD8 cells." (PMID 26928938, 2016). "Independent associations with moderate-to-significant liver disease based on APRI included HBV (Odds ratio, OR 2.37, P < 0.001), HCV (OR 9.64, P<0.001), CD4 count≤200 cells/μL (OR 2.55, P<0.001) and age ≥30 years (OR 1.80, P=0.001)." (PMID 26979535, 2016). "Studies have shown that the CD4+ cell count is depressed with hepatitis C co-infection and liver disease." (PMID 24695533, 2014). "Recent guidelines recommend that CART generally be initiated first to slow liver disease progression and increase CD4 cell count, bearing in mind that some drugs should be avoided while others should be monitored for hepatotoxicity." (PMID 26316953, 2013). "Patients with more severe liver disease (above F2) were older with a mean age of 43.9 vs. 39.8 years (p = 0.043) and had lower CD4-cell counts with a mean value of 344 vs. 458 cell/mm3 (p = 0.046)." (PMID 23497042, 2013). "HBV is thought to mediate destruction of CD4 cells through T-cell activation or splenic sequestration seen in advanced liver disease." (PMID 26316953, 2013).